CD4 (CD4 molecule)
Diseases named in the same sentence as CD4 in open-access papers (continued):
Sharing a sentence is not in itself a finding about the gene and the disease.
tumor (continued). "These TAM subgroups interact with CD8 + T cells, CD4 + T cells, and dendritic cells (DCs), forming a complex network that significantly influences the tumor immune status." (PMID 41035074, 2025). "Numerous cancer cells within the body express both MHC I and MHC II, with MHC II play a key role in antigen presentation of CD4+ T-lymphocytes, the significance of CD4+ T- lymphocytes in anti-tumor immunity is increasingly recognized and valued." (PMID 39931080, 2025). "Lymph stromal cells such as lymph node endothelial cells (LECs) help tumor cells complete immune escape by promoting the expansion of CD4+ CD25- Tregs with PD-L1 or NO and inhibiting the proliferation of other T cells." (PMID 40216744, 2025). "In NPC xenografts, TCR‐engineered CD4+ T cells effectively killed EBNA1‐expressing tumours while activating CD8+ T cells for a synergistic anti‐tumour response." (PMID 40401927, 2025). "Loss of MHC-II through the CIITA gene impairs the presentation of tumor-derived antigens to CD4+ T-helper cells, affecting dendritic cell priming and potentially impacting DC function cross-presentation." (PMID 41295262, 2025). "Overall immune cell density was higher in the tumour stroma, particularly driven by an increase in CD4 and CD8 T-cells, APCs and B cells." (PMID 39349005, 2025). "In fact, a high density of T lymphocytes within the tumor bulk, including CD4+ and CD8+ cells, typically correlates with improved outcomes." (PMID 39995659, 2025). "CD8+ T cells directly kill tumor cells by recognizing tumor antigens, while CD4+ T cells enhance the function of CD8+ T cells and NK cells by providing co-stimulatory signals and cytokines." (PMID 40936903, 2025). "Depletion of either CD4+ or CD8+ T cells resulted in tumor growth, whereas isotype-treated KP1 TAS1440 tumors regressed." (PMID 40627448, 2025). "Each subtype of T cells, such as CD8+, CD4+, and regulatory T cells (T regs), plays distinct yet interrelated roles in response to infection and tumor development." (PMID 40227295, 2025). "RIVA efficiently stimulates dendritic cell maturation, eliciting innate immune activation effects through NK cells and elicit adaptive immune anti‐tumor responses through CD4+ and CD8+ T cells." (PMID 40619603, 2025). "Delving deeper, this study revealed that the tumor-suppressive effects of oral antibiotics were associated with an increased infiltration of Tc1 (IFN+CD8+CD3+) and Th1 (IFN+CD4+CD3+) cells within the tumor microenvironment." (PMID 40243755, 2025). "Consistent with the slower tumor growth in the triple therapy + LC cohort, we measured increased cytotoxic CD4+GrB+, CD4+, and CD8+ IFNγ+TNFα+ and a trend to more memory T cells and fewer CD8+ regulatory T cells (Tregs) in the tumors." (PMID 41171165, 2025). "During fatty liver graft injury, arachidonic acid activates the NLRP3 inflammasome in MDSCs through FATP2, leading to increased IL-17 secretion by CD4+ T cells and promoting tumor recurrence post-transplantation." (PMID 39990210, 2025). "While immune surveillance is crucial for anti‐tumour immunity, tumour cells can secrete factors that suppress CD4+ and CD8+ lymphocyte activity, resulting in lymphocytopenia and facilitating immune evasion." (PMID 40631494, 2025). "Lymphocyte activation gene-3 (LAG-3) is a type I transmembrane protein structurally similar to CD4 and functions as an inhibitory co-receptor critical in autoimmune diseases, tumor immunity, and anti-infective immunity." (PMID 39911397, 2025). "Meanwhile, the sleep deprivation group exhibited an elevated proportion of CD4+ T cells in the tumor tissue, while the proportion of CD8+ T cells was significantly reduced." (PMID 40276761, 2025). "The presence of Th1 CD4+ T-cells and cytotoxic CD8+ T-cells in the tumor microenvironment has been associated with an improved prognosis, while FOXP3+ regulatory T-cells are associated with the downregulation of the immune response and a poorer prognosis." (PMID 40362529, 2025).
tumor (continued). "After tumor challenge in 4T1 model, also CD4+ cells were the dominant subtype, comprising around 56%, while in advanced tumors, CD8+ T cells rose to 35.86% (P=0.012), caused a reduction in CD4/CD8 ratio from 2:1 to 1.58:1." (PMID 39877637, 2025). "In vitro experiments suggest that eosinophils contribute to tumor cell eradication by engaging in complex cellular interactions with B lymphocytes, Th1/Th2 CD4+ T cells, and other granulocytes." (PMID 40761780, 2025). "Consistent with prior studies, HIV-positive patients with lower CD4+ counts exhibited higher rates of advanced tumor burden." (PMID 40969752, 2025). "We then separately transferred an equivalent number of CD4+ T cells isolated from M002-treated tumor or the saline-treated counterpart into Tcrα−/− recipients that were then implanted with GSC005 cells at day 3 post-transfer." (PMID 39885128, 2025). "Significantly, GSDMD deficiency or its inactivation in CD4+ T cells disabled CD8+ T cell–mediated antitumor immunity and caused tumor outgrowth in mice." (PMID 40759573, 2025). "CD8+ and CD4+ T cells can differentiate into tumor-infiltrating PD-1+ effectors and memory T cells after activation." (PMID 40061134, 2025). "By classifying the immune cells in the TME, we calculated the proportions of tumor-infiltrating CD4+ T cells and CD8+ T cells and M2-type macrophages in each group." (PMID 40943568, 2025). "IFN-γ-loaded nanoparticles can be administered either intratumorally or systemically to aid in tumor rejection by enhancing CD4+ T-cell function and facilitating CTL priming." (PMID 40860882, 2025). "Among them, T cell CD4+ memory resting took the dominant role in thyroid tissue and showed a significant decrease in tumor compared to the para-cancerous tissue." (PMID 40552117, 2025). "We observed fewer surviving CD45−GFP+ tumor cells in mice transferred with M002-treated CD4+ T cells than mice given saline-treated CD4+ T cells." (PMID 39885128, 2025). "B cells, characterized by the CD19 surface marker, primarily secrete antibodies against tumor-associated antigens and coactivate CD8+ T cells in conjunction with CD4+ T cells." (PMID 40958865, 2025). "In contrast, in LGG, LSM2 expression positively correlated with tumour purity (r = 0.154, p < 0.001) and CD4+ T cell infiltration (r = 0.161, p < 0.001), and negatively correlated with CD8+ T cell infiltration (r = -0.178, p < 0.001)." (PMID 40365337, 2025). "Vin treatment significantly enhanced the infiltration of CD8+ T cells, CD4+ T cells, and NK cells in the tumor compared to the control group." (PMID 40866941, 2025). "Studies show increased Treg infiltration in CRC tissues compared to normal tissues, correlating with higher TNM stages and elevated mRNA expression of Foxp3, IL-10, and TGF-β1 in tumor-infiltrating CD4+ T cells." (PMID 40308582, 2025). "When CD4 + is activated by the corresponding tumor antigen, it can secrete various cytokines to exert anti-tumor effects." (PMID 41040673, 2025). "Its reduced expression in CRC tissues and CD4+ T cells implicate omega-3 PUFA-mediated epigenetic repression in compromised tumor immunosurveillance." (PMID 40990012, 2025). "This analysis revealed that the presence of MVI, incomplete tumor capsule, and low CD4+ T cell infiltration in the CT region also were independent risk factors for decreased RFS." (PMID 41212769, 2025). "Exposure to the cervical or vulvar TME enables pDCs to promote the differentiation of naïve CD4+ T cells into Tregs, further enhancing the immunosuppressive state of the tumor." (PMID 40539072, 2025). "In the tumor microenvironment, signaling overactivation can inhibit the proliferation and activation or apoptosis of CD4 and CD8T cells, thereby promoting the negative regulation of immunity and inhibiting the immune effect of T cells and lymphocytes." (PMID 40070839, 2025).
tumor (continued). "CD8+ recognises tumour cells sign their MHC class-I receptor and causes the tumour cells to lyse whereas CD4+ can be differentiated into several T helper (Th) cells and Treg cells that secrete cytokines to protect the host from pathogens." (PMID 40407951, 2025). "High SHCBP1 expression is linked to greater infiltration of tumor-associated macrophage (TAM), CD4+ naïve T cells, CD8+ T cells, and neutrophils, as well as elevated levels of immune checkpoint proteins, including PD-L1 and TGFBR1 in multiple tumor types." (PMID 41009347, 2025). "The phenotype of T cells at the tumor site was also analyzed, and the data showed that more memory CD4+ and CD8+ T cell phenotypes in IL15C-NKG2D-CAR T cells." (PMID 40625735, 2025). "A comprehensive understanding and investigation of the functions and regulatory mechanisms of CD4+ T cells are therefore crucial for the advancement of novel tumor immunotherapies and the enhancement of treatment efficacy." (PMID 40857744, 2025). "We found higher ratios of vessels to tumor CD4+ cells in ephrinB2 knockout mice, suggesting increased CD4 + T cell accumulation in the TME." (PMID 39489818, 2025). "Through dimensionality reduction and cellannotation, we obtained the gene expression information of tumor microenvironment cells, including TAMs, CD4+ T cells, and CD8+ T cells." (PMID 40539047, 2025). "The activated CD8+ T cells kill tumor cells directly, while CD4+ T cells support this process, ultimately leading to the suppression of distant tumors." (PMID 40746718, 2025). "Recent studies have highlighted the potential contribution of CD4+ T cells with cytotoxic activity (CD4 CTLs) to anti-tumor immunity." (PMID 40070836, 2025). "Previously, neoantigen vaccines were shown to stimulate multifunctional CD4+ T cells to differentiate into CD4+ Th1 cells in preclinical mouse tumor models or clinical trials with limited sample sizes, thereby inducing a prolonged CD8+ T-cell response." (PMID 40556945, 2025). "In some settings, IL-4 upregulates CD30 expression on activated CD4+ T cells, thereby increasing the density of BV targets on the tumor surface." (PMID 40864740, 2025). "In contrast, N2 neutrophils promote tumor growth by recruiting immunosuppressive CD4+ T-cells and upregulating CCL2, which stimulate angiogenesis." (PMID 40299416, 2025). "CD4+ Tregs were increased in the LNs of the triple therapy + LC cohort and in the tumor of the triple therapy mice." (PMID 41171165, 2025). "A VACV strain expressing CCL5 induced significant infiltration of DCs, CD4+ T cells, and NK cells, effectively suppressing tumor growth in the MC38 murine model." (PMID 40723208, 2025). "CD4+ T cells play complex and multifaceted roles in tumors, primarily by promoting tumor control through cytokine release and related helper cell functions." (PMID 40612935, 2025). "Generally, CD8+ CTLs mediate direct tumor cell killing through granzyme/perforin‐dependent mechanisms, while CD4+ T helper (Th) and Treg cells maintain immune homeostasis via cytokine‐mediated regulation." (PMID 41427020, 2025). "MHC class II presentation leads to CD4+ T cell activation, which in turn promotes B cell activation and antibody production, contributing to tumor cell elimination." (PMID 40427029, 2025). "CD4+ T cells are a critical component of the immune system and play essential roles in immune regulation and anti-tumor responses." (PMID 41018226, 2025). "Through immune cell depletion experiments, we determined that the anti-tumor effects of HVEM-Fc primarily require CD4+ and CD8+ T cells." (PMID 39979981, 2025). "The results showed increased infiltration of tumor-suppressing cytotoxic T cells (CD4 and CD8 T cells) in the FeMn@R@H group." (PMID 40486836, 2025). "Third, succinate also inhibits TIL anti-tumor activity: Succinate is taken up by MCT1 in CD4+ and CD8+ T cells, and this accumulated succinate blocks metabolic flux through the TCA cycle by inhibiting the enzyme succinyl CoA synthetase (SUCLA2)." (PMID 39796781, 2025).
tumor (continued). "This study highlights MVI absence, tumor capsule integrity, and CD4+ T cell infiltration as key predictors of RFS in HCC patients receiving neoadjuvant immunotherapy." (PMID 41212769, 2025). "Further research is required to explore the molecular mechanisms regulating B7-H3 and LAG3 expression on CD4 CTLs and to validate these findings in other tumor types." (PMID 40070836, 2025). "The results showed that the Sirt1‐KO group exhibited a significant decrease in the infiltration of immunosuppressive cells, such as M2‐type macrophages (Cd11b+Cd206+) and Treg cells (Cd4+Cd25+Cd127−), within the tumor tissue." (PMID 39783838, 2025). "These include CD4, FOXP3 positive regulatory T-lymphocytes (Tregs), myeloid derived suppresser cells (MDSCs) recruited from the bone marrow and tumour-associated macrophages." (PMID 40427006, 2025). "Functionally, tsMHC‐II enables direct presentation of tumour‐derived antigens to CD4+ T cells, bypassing the need for intermediary APCs and thus facilitating local T‐cell activation within the tumour microenvironment." (PMID 40673641, 2025). "The CD4+ T cell subset plays a pivotal role in anti-tumor immunity, tumor immune evasion, tolerance mechanisms, TIME and the maintenance of immune homeostasis." (PMID 40352921, 2025). "CXCL8 also exhibits dual roles in immune regulation: While it enhances anti-tumor immune responses via CD4+ T cell activation, it can also promote immunosuppression by inducing PD-L1+ macrophages." (PMID 40299331, 2025). "microRNA-200a promoted tumor growth by increasing Foxp3+ regulatory T cells while decreasing the proportions of CD4+, CD8+, and IFN-γ+ cytotoxic T cells." (PMID 39615277, 2025). "In the present study, we highlight the pivotal role of MZF1 in regulating immune responses, particularly in immune cells such as CD4+ T cells and monocytes/macrophages, suggesting its involvement in the tumor immune microenvironment." (PMID 40655141, 2025). "The results of multiple immune infiltration algorithms demonstrated that the low-risk group generally had a richer infiltration of anti-tumor immune cells, such as CD8+ T cells, CD4+ T cells, active NK cells, B cells, and so on." (PMID 40703522, 2025). "Competitive utilization of aerobic glycolysis by tumor cells leads to limited glucose availability for T cells, suppressing CD4+T cell-mediated immunosurveillance and facilitating CD8+T cell exhaustion." (PMID 41184283, 2025). "Meanwhile, tumor‐infiltrating CD11c+ DCs, CD4+ T cells, and CD8+ T cells were also upregulated following PRMT5i treatment combined with CPT‐11." (PMID 40344511, 2025). "CD4+ T helper cells promote anti-tumour immunity by orchestrating dendritic cell activation and licensing, facilitating CD8+ T cell recruitment, and supporting B cell maturation." (PMID 41459509, 2025). "High succinate concentrations in the TME also increase the expression of SUCNR1 on many tumor cells, but CD4+ and CD8+ T cells instead downregulate SUCNR1 in response to succinate exposure, probably owing to its deleterious effects in these cells." (PMID 39796781, 2025). "In gastrointestinal cancers, DNA methyltransferases DNMT1 and DNMT3B mediate methylation of the CIITA promoter, silencing its expression and consequently blocking HLA-DR induction, which limits tumor suppressor functions of CD4+ lymphocytes." (PMID 41050070, 2025). "The TME is a dynamic system orchestrated by complex components, including stromal cells, CD4+ and CD8+ T cells, natural killer (NK) cells, tumor-related endothelial cells, cancer-associated fibroblasts (CAFs), and tumor-associated macrophages (TAMs)." (PMID 41007347, 2025). "CFRI-mediated PTT and TLR7 agonist release promoted DC maturation, enhancing CD8+ and CD4+ T cell activity, key for tumor elimination and preventing metastasis." (PMID 40040955, 2025).
tumor (continued). "Recent studies have underscored the critical role of immune cells, including CD4+ T cells, CAFs, MDSCs, neutrophils, and macrophages, in shaping responses to tumor immunotherapy." (PMID 40842984, 2025). "In this analysis, we found that cytotoxic CD4+ T cells largely correlated with reduced tumor growth in the triple therapy group, with the smallest tumors having the highest frequencies of CD4+ T cells with higher IFNγ and TNFα expression." (PMID 41171165, 2025). "To further clarify the role of C6orf120 in tumor immunity, we analyzed its association with seven key immune cell types (B cells, CD8+ T cells, CD4+ T cells, M1 macrophages, M2 macrophages, neutrophils, and dendritic cells) in LIHC using the GEPIA database." (PMID 39388711, 2025). "During the second phase of CD8+ T cell activation, CD4+ T cells promote the accumulation, expansion, trafficking, and differentiation of tumor-specific CD8+ T cells within tumors." (PMID 41030446, 2025). "The tumor histology of tumor-infiltrating immune cell subsets (CD4+, CD8+, CD11c+) reveals significant increases in CD11c+ populations, consistent with TLR7/8 agonism." (PMID 40573201, 2025). "Tissue-resident memory CD4+ T cells have also shown promise as targets for immunotherapeutic intervention due to their robust, localized responses to tumor antigens." (PMID 40475782, 2025). "FOXP3+ Treg cells are abundant at the differentiation terminal states of tumor-infiltrating CD4+ T cells." (PMID 41008548, 2025). "A substantial body of research suggests that the GLP-1 signaling pathway plays a pivotal role in regulating the infiltration of various anti-tumor immune cells, including CD4 + T cells, neutrophils, NK cells, macrophages, and dendritic cells." (PMID 40140925, 2025). "Th2 cells are a subset of CD4+T cells that promote tumor progression by secreting cytokines such as IL-10 and IL-13 to enhance angiogenesis and inhibit the cytotoxic effects of CD8+ T cells." (PMID 41040664, 2025). "The CD8+ T cell population in the primary tumor increased to 14.0%, and the CD4+ T cell population increased to 40.8%." (PMID 39743555, 2025). "The few functional studies of CD4+CD8+T cells reported either anti-tumor or antiviral activities: In the tumor model they were a heterogenous population with cytotoxicity and reactivity towards cancer cells." (PMID 40283908, 2025). "The activation of antitumor CD4+T cells upon adoptive transfer of tumor-specific Tc9s occurs as a result of IL-24 secretion and recruitment of CCR7+cDC2s (conventional type 2 DCs) into tumor-draining LNs, which prime host CD4+T cells against relapsing tumors." (PMID 41009359, 2025). "This suggests that CD4+ TILs are not only reduced in number but also functionally impaired within the tumor microenvironment." (PMID 40699668, 2025). "In contrast, CD4 T cells exhibited an opposite trend, with a noticeable increase in tumor regions and a significant increase in AS progression." (PMID 40786043, 2025). "CD4+ T cells play a key role in halting tumor development by eradicating precancerous, oncogene-induced senescent hepatocytes through immunological mechanisms." (PMID 41294748, 2025). "Most notably, after Vk*myc tumor implantation, we observed substantial increases in both CD4+ and CD8+ T cell populations in the spleens of ARRB1 knockout mice compared to wild-type littermate controls." (PMID 41373634, 2025). "Treatment with aPDL1-GEM@Gel not only significantly inhibited tumor growth in the B16F10 mouse melanoma tumor model, but also increased infiltration of CD4+ and CD8+ T-cells and induced systematic immune responses." (PMID 40270972, 2025). "Roxadustat treatment significantly increased both the number and percentage of CD8+ and CD4+ tumor-infiltrated lymphocytes (TILs)." (PMID 40343532, 2025). "Meanwhile, CD4+ Th2 cell–mediated immune response has traditionally been viewed as favoring tumor growth." (PMID 39782693, 2025).